CDADC1 (cytidine and dCMP deaminase domain containing 1)
Description:
Catalyzes the deamination of dCTP to dUTP, exhibiting a strong substrate preference for dCTP over CTP. No deaminase activity toward 5-methyl-dCTP, cytidine, or deoxycytidine. May play an important role in testicular development and spermatogenesis. In addition to its role on endogenous nucleotides, it deaminates the active triphosphate forms of the cytidine analog drugs, gemcitabine (dFdCTP) and decitabine (5-aza-dCTP), rendering them susceptible to inactivation by deoxyuridine triphosphatase (DUT). This process limits drug-induced cytotoxicity and contributes to cellular resistance to gemcitabine and decitabine.
Synonyms: NYD-SP15; bA103J18.1
Tractability: No criterion of Open Targets' tractability assessment is met for any kind of drug.
Gene: Protein-coding gene on chromosome 13 (49,247,917 to 49,293,485, forward strand). Ensembl gene ENSG00000102543.
Subcellular location: Cytoplasm; Nucleus
Subcellular location (Human Protein Atlas): Nucleoplasm
Gene Ontology:
Molecular function: cytidine deaminase activity; dCTP deaminase activity; importin-alpha family protein binding; protein homodimerization activity; zinc ion binding; dCMP deaminase activity; hydrolase activity
Biological process: DNA cytosine deamination; dUTP biosynthetic process; protein homotrimerization
Cellular component: cytoplasm; nucleus
Genetic constraint (gnomAD): Loss-of-function variants: 24 observed, 36.79 expected, observed/expected ratio (o/e) 0.65, 90% interval 0.47 to 0.92. The upper end of that interval is the gene's LOEUF score, 0.92, which puts it in group 3 of 6, group 1 being the genes least tolerant of losing a copy. Missense variants: 410 observed, 482.06 expected, observed/expected ratio (o/e) 0.85, 90% interval 0.78 to 0.92. Synonymous variants: 151 observed, 162.11 expected, observed/expected ratio (o/e) 0.93, 90% interval 0.81 to 1.07.
Homologues: Orthologues: chimpanzee CDADC1 (100% identical), macaque CDADC1 (99% identical), rabbit CDADC1 (95% identical), guinea pig CDADC1 (93% identical), dog CDADC1 (92% identical), mouse Cdadc1 (89% identical), pig CDADC1 (89% identical), rat Cdadc1 (87% identical), tropical clawed frog cdadc1 (66% identical), zebrafish cdadc1 (51% identical). Paralogues in human: DCTD (10% identical).
Diseases named in the same sentence as CDADC1 in open-access papers:
CDADC1 is named in the same sentence as 24 diseases in open-access papers, as found by Europe PMC text mining. Sharing a sentence is not in itself a finding about the gene and the disease. The quoted sentences say what the papers report.
acute myeloid leukemia (1 paper, 2025). Acute myeloid leukemia (AML) is a group of neoplasms arising from precursor cells committed to the myeloid cell-line differentiation. "Given consistent CDADC1 expression across cancer types but with higher levels in leukemia, we compared decitabine sensitivity of WT and CDADC1-deficient cell lines from human T-cell acute lymphoblastic leukemia (Molt-4 and Jurkat), acute myeloid leukemia (THP-1), and chronic myeloid leukemia (K562)." (PMID 40504152, 2025).
B cell lymphoma (1 paper, 2025). "We also ablated Cdadc1 in the mouse B cell lymphoma line CH12F3." (PMID 40504152, 2025).
COVID-19 (1 paper, 2024). A disease caused by infection with severe acute respiratory syndrome coronavirus 2. "Genes in this pathway, AICDA, CDADC1, CDA and APOBEC3D, were regulated in opposite directions (only AICDA was statistically significantly downregulated in SLE and CDA up in COVID-19), while APOBEC3A and APOBEC3B were significantly upregulated in COVID-19, but not SLE." (PMID 38302132, 2024).
kidney carcinoma (1 paper, 2025). Primary or metastatic malignant neoplasm involving the kidney. "CDADC1 expression was not prognostic in pancreatic or most other cancers, except for kidney carcinoma and lung adenocarcinoma in which higher levels correlated with longer survival." (PMID 40504152, 2025).
large-cell lung carcinoma (1 paper, 2025).
leukemia (1 paper, 2025). A malignant (clonal) hematologic disorder, involving hematopoietic stem cells and characterized by the presence of primitive or atypical myeloid or lymphoid cells in the bone marrow and the blood. "Overexpression of active CDADC1 did not change sensitivity to cytarabine, a cytosine arabinoside used against leukemia and lymphoma and has a 2′OH, aligning with CDADC1’s biochemical preference for 2′-deoxynucleotides." (PMID 40504152, 2025). "Using CRISPR-Cas9 we deleted CDADC1 in HEK293T and two human leukemia cell lines, which showed the highest expression among various cell types." (PMID 40504152, 2025).
leukopenia (1 paper, 2025). "Gemcitabine caused pronounced thrombocytopenia and leukopenia, with highly reduced myeloid and lymphoid cells within the bone marrow, in Cdadc1−/− mice." (PMID 40504152, 2025).
pancreatic cancer (1 paper, 2025). "On one hand, CDADC1 deficiency enhances the sensitivity of human cancer cells to gemcitabine and decitabine, increasing the antitumor efficacy of gemcitabine in mouse models of pancreatic cancer at a dose equivalent to ~380 mg/m2." (PMID 40504152, 2025). "CDADC1 expression was largely similar in cancer versus corresponding normal tissues but appeared higher in pancreatic cancer, where gemcitabine is standard of care." (PMID 40504152, 2025). "Gain- and loss-of-function assays in cancer cell lines, along with ectopic mouse models of pancreatic cancer, show that CDADC1 reduces these drugs’ efficacy." (PMID 40504152, 2025). "Similarly, CDADC1 KO human KP-4 pancreatic cancer cells showed strong gemcitabine sensitivity in athymic mice." (PMID 40504152, 2025).
prostate carcinoma (1 paper, 2025). A carcinoma that arises from epithelial cells of the prostate gland. "A fraction of bladder, sarcoma, and prostate cancer samples showed very low CDADC1 expression, correlating with CDADC1 copy number losses." (PMID 40504152, 2025).
viral infection (1 paper, 2025). "Moderate upregulation of CDADC1 in response to virus infection was only observed in some adenocarcinomas, but was not significant." (PMID 40324085, 2025). "To test this hypothesis, we queried OncoDB, which summarizes data from The Cancer Genome Atlas for possible upregulation of CDADC1 in response to viral infection in various types of malignancies." (PMID 40324085, 2025). "Similar to prokaryotic dCTP deaminases in antiphage defense, CDADC1 may be activated/overexpressed in response to viral infection." (PMID 40324085, 2025). "However, CDADC1 is not significantly overexpressed in human cell lines in response to (chronic) viral infection." (PMID 40324085, 2025).
cancer (2 papers, 2025). A tumor composed of atypical neoplastic, often pleomorphic cells that invade other tissues. "CDADC1 deficiency in cancer cells increases these drugs’ efficacy but also protects mice from lethal gemcitabine-induced toxicity." (PMID 40504152, 2025). "CDADC1 deficiency sensitizes cancer cells to these drugs, but full-body deficiency leads to toxicity in gemcitabine-treated mice." (PMID 40504152, 2025). "On the other hand, we demonstrate that endogenous CDADC1 confers substantial resistance to gemcitabine and decitabine in cancer cells." (PMID 40504152, 2025). "Thus, CDADC1 promotes gemcitabine resistance in human cancer cells, and its deletion enhances gemcitabine efficacy in vivo, primarily by increasing cytostatic and apoptotic effects, although we cannot formally rule out a contribution of the adaptive immunity." (PMID 40504152, 2025). "Cancers with low CDADC1 may be naturally more sensitive to dC analogs or differentially benefit from CDADC1 inhibition while avoiding severe toxicity." (PMID 40504152, 2025). "Thus, CDADC1 underpins a previously unrecognized mechanism of intrinsic chemoresistance in cancer cells and has a nonredundant role in protecting from gemcitabine toxicity." (PMID 40504152, 2025).
CDADC1 also shares sentences with these, for which no sentence is quoted: infection (2 papers); acute lymphocytic leukemia (1); adenocarcinoma (1); chondrosarcoma (1); chronic myeloid leukemia (1); lung adenocarcinoma (1); lymphoma (1); neuroblastoma (1); pancreatic ductal adenocarcinoma (1); sarcoma (1); T-cell acute lymphoblastic leukemia (1); Thrombocytopenia (1); tumor (1).